CTLA4 (cytotoxic T-lymphocyte associated protein 4)
Diseases named in the same sentence as CTLA4 in open-access papers (continued):
Sharing a sentence is not in itself a finding about the gene and the disease.
tumor (continued). "Blockade of CTLA-4 with a monoclonal antibody has therefore been explored as a therapeutic strategy to enhance anti-tumor immunity." (PMID 37763109, 2023). "Strikingly, addition of anti-Ly6C to the anti-PD-1/CTLA-4 combination herein proved to not only prevent resistance from occurring but also produced complete tumor rejection." (PMID 37449205, 2023). "While anti-CTLA4 therapy controlled tumor growth effectively and cured ∼70% of the animals, the combination therapy was not toxic in the animals but did not offer any further therapeutic benefit." (PMID 36068918, 2023). "As such, CTLA-4 inhibition leads to increased T-cell activation and a reduction in mouse tumor size." (PMID 37197667, 2023). "TGF-β can upregulate the expression of PD1 and CTLA-4 on T lymphocytes and attenuate the cytotoxicity of T lymphocytes toward tumor cells in vitro and in vivo." (PMID 36776837, 2023). "Tumor-infiltrating monocyte-derived dendritic cells have potent antigen-presenting capacity, thereby enhancing the antitumor activity of anti-PD-1/CTLA-4 therapy." (PMID 37449205, 2023). "CTLA-4 blockade also increases IFNγ and Cxcl9 expression in immunogenic tumor cells, which are crucial in type 1 immunity and vessel normalization as well as T cell recruitment." (PMID 37587450, 2023). "ICIs can restore T-cell function by blocking the binding of PD-1 or CTLA-4 to ligands, thus achieving the purpose of tumor therapy." (PMID 36647390, 2023). "The mice were injected with antibodies to CTLA-4 (Bio X Cell, USA) (250 μg per mouse, intraperitoneally on days 7, 8, 11, and 12 of the tumor growth)." (PMID 38435479, 2023). "While CD8+ T cell depletion significantly restored tumor growth in mice receiving dual IL-6/CTLA-4 blockade, CD4+ depletion resulted in pronounced tumor growth." (PMID 36881480, 2023). "As a new class of targeted anticancer drugs, ICIs target the immune tolerance pathways of tumor cells, such as PD-1, PD-L1 and CTLA-4, to kill tumor cells." (PMID 36600271, 2023). "Here, we investigated, using our bioluminescent, dual color, T-cell reporter mouse, termed TbiLuc, T-cell location and function during murine PDAC tumor growth and checkpoint blockade treatment with anti-PD-1 and anti-CTLA-4." (PMID 37497236, 2023). "A higher percentage of CTLA-4 positive immune cells was observed in patients with advanced stage III disease in the tumor microenvironment." (PMID 37305822, 2023). "Immunosuppressive checkpoint ligand molecules (such as PD-L1 and CTLA-4) can biologically limit T-cell growth and function and are commonly increased in tumor cells during immunotherapy." (PMID 37649123, 2023). "We also found that the combination of DSP-0509 with anti-CTLA-4 antibody resulted in increased effector memory T cells in the tumor." (PMID 36793737, 2023). "The associations of mRNA expression between CRABP2 and three immune checkpoint molecules (PDCD1, CD274 and CTLA4) were examined in 33 different tumor types from the TCGA database using the TIMER2.0 and Xiantao tools." (PMID 38186580, 2023). "Anti-PD-1/CTLA-4 treatment inhibits tumor progression in a CD4+ and CD8+ T cell-dependent manner, with CD4+ and CD8+ T cells working in an orchestrated fashion to control tumors." (PMID 37449205, 2023). "Recent studies have highlighted the role of miRNAs in regulating immune checkpoint (PD-1, PD-L1, and CTLA-4) gene expression and their importance as regulators of T-cells and tumor cells." (PMID 37197667, 2023). "CTLA4+/IFN-γ+ lymphocytes in the lymph node correlated with PD-L1 in the tumor at a significance level of 93% (χ2 = 7.1; p= 0.069)." (PMID 36979688, 2023). "For instance, the histone deacetylase inhibitor Belinostat improves the anti-tumor activity of CTLA-4 in a subcutaneous Hepa129 murine HCC model, reflecting the synergistic effect of combined therapy." (PMID 37903974, 2023).
tumor (continued). "Similar observation in CD8+ T cell response to ICB, CD4+ T cells have also been reported to be required for ICB, especially CTLA‐4 blockade in tumor patients." (PMID 37829505, 2023). "Second, although Teffs bind to tumor cells, tumor cells can avoid attack via immune checkpoints (ICTs), such as PD-L1 and CTLA4." (PMID 37408372, 2023). "CTLA-4 expression followed a gradient from tumor periphery to the tumor center of keratinizing HNSCC, a gradient observed similarly to the adjacent epithelium." (PMID 37415208, 2023). "As with cuSCC, the CTLA-4 and PD-1 receptors are considered key pathways in allowing for unchecked tumor growth and several of the same monoclonal antibodies are also being studied in BCC." (PMID 37444461, 2023). "Regarding the sites where immune checkpoint molecules work, it is now considered that CTLA-4 acts as a negative regulator of the initial activation of T cells in regional lymph nodes, and PD-1 ligands suppress T-cell activation in the tumor microenvironment." (PMID 37370399, 2023). "Blockage of PD-1 and/or CTLA-4 can lead to the stimulation and augmentation of anti-tumor effects via the activation of tumor-specific cytotoxic T-cells and inhibition of regulatory T cells (Tregs)." (PMID 36891313, 2023). "Surface molecules such as PD-L1, PD-1, and CTLA4 suppress T-cell activation, enable tumor cells to evade immune surveillance, and foster a supportive microenvironment for the CRC cell." (PMID 37760801, 2023). "We performed sensitivity analyses with OVT alone and also with the combined therapy of OVT and anti-CTLA-4 to determine parameters that are most significantly impacting the tumor response to treatments." (PMID 36766849, 2023). "Strategies targeting Tregs to increase anti-tumor immunity, including antibodies against CTLA-4, OX40, 4-1BB, and ICOS, have attracted attention." (PMID 37729184, 2023). "Addition of anti-Ly6C to the anti-PD-1/CTLA-4 combination prevented resistance from forming and importantly facilitated complete tumor elimination." (PMID 37449205, 2023). "CTLA-4 monoclonal antibody clears Treg in tumor effectively through FcR mediated ADCC (antibody-dependent cell-mediated cytotoxicity), thus relieving immunosuppressive of Treg to achieve anti-tumor." (PMID 36911712, 2023). "In HNSCC, CD8+ T cells that underwent clonal expansion during ICB treatment expressed elevated tissue-resident memory (CD103+ZNF683+) and cytotoxicity programs (GZMB+PD-1+CTLA-4+) and show tumor-specific recognition." (PMID 37881432, 2023). "The association between a better prognosis with CTLA-4 overexpression in tumour infiltrating lymphocytes (TILs) implied the crucial role of CTLA-4 in escape immune response by tumours." (PMID 36813833, 2023). "PD-1, PD-L1, and CTLA-4 are established immunosuppressive ICPs, and are generally recruited by tumor cells to promote immune evasion." (PMID 36759763, 2023). "The authors showed systemic bacterial-derived SCFAs modulate anti-CTLA-4-stimulated immune responses as well as their anti-tumor effectivity." (PMID 37627114, 2023). "In contrast, PPARγ agonists restored CD8+ Teffs pools, potentiated vaccine-driven anti-tumor response in combination with CTLA4 Ab in vivo, and reduced chemokine expression in tumor cell co-cultures with human peripheral blood mononuclear cells in vitro." (PMID 37686465, 2023). "Of note, recent analysis has highlighted the potential for CTLA-4-expressing tumour-infiltrating follicular regulatory T cells (Tfr) to limit the effectiveness of PD-1 inhibitors." (PMID 36818683, 2023). "USP5 inhibition in combination with Trametinib or anti-CTLA-4 has an additive effect on suppressing tumor growth in mice." (PMID 37208329, 2023). "Tregs, like CD8+ T cells, infiltrate tumor stroma, whereas CTLA4-expressing Tregs hinder T cell activation." (PMID 37892995, 2023). "We were intrigued by the impact of the immune checkpoint inhibitors PDL1/CTLA-4 on the tumor microenvironment of HCC." (PMID 37575252, 2023).
tumor (continued). "The checkpoints, such as the over-expressed cytotoxic T lymphocyte associated antigen 4 (CTLA-4) and programmed death ligand-1 (PD-L1), hinder the recognition of tumor cells by T cells." (PMID 36597214, 2023). "CTLA4 blockade through administration of anti-CTLA4 mAb via LDDS to tumor bearing LN was found to successfully lead to total tumor rejection in about 67% of treated subjects." (PMID 37259163, 2023). "Recent studies observed that the monotherapy with anti-PD-1 or anti-CTLA-4 antibodies can induce anti-tumor effects in prolonged survival of cancer patients." (PMID 36721212, 2023). "In this context, PD-1 and CTLA-4 inhibitors have been studied extensively; they have shown dynamic and durable tumor regression in patients with EC, CC, and OC." (PMID 36793735, 2023). "Strikingly, when we used the anti-Ly6C antibody (clone Monts 1) to block Ly6C, the resistance to anti-PD-1/CTLA-4 was completely suppressed in the aggressive KP 344SQ tumor model." (PMID 37449205, 2023). "As reported, the impacts of the DC/tumor fusion vaccine are coupled with the impacts from the mAb targeting CTLA-4." (PMID 37419930, 2023). "CTLA-4 blocking antibody (MDX-CTLA4) stimulated extensive tumor necrosis with lymphocyte and granulocyte infiltrates in vaccinated patients with metastatic OC." (PMID 37368179, 2023). "Based on these backgrounds, it is conceivable that the combination of anti-CTLA-4 antibody with DSP-0509 activated CTLs in the tumor microenvironment via activation of CTLs and Treg depletion." (PMID 36793737, 2023). "Immune checkpoint inhibitors (ICIs), including programmed cell death-1 (PD-1), programmed death-ligand 1 (PD-L1), and cytotoxic T-lymphocyte antigen 4 (CTLA4) inhibitors, are a modality of tumor immunotherapy." (PMID 38188686, 2023). "As expected, in contrast to HPV mRNA-LNP vaccination alone or ICB alone, the combination of HPV mRNA-LNP vaccination and LAG3/CTLA4 blockade exacerbated synergistic effects on tumor growth." (PMID 37773254, 2023). "In contrast to thermal ablation such as RFA and MWA, which relies on a temperature typically above 60 ̊C, local hyperthermia (42.5 ̊C for 20 min) with anti-CTLA-4 was also shown to enhance the anti-tumor response." (PMID 37251920, 2023). "Currently, the FDA has approved the ICIs CTLA-4 and PD-1, as well as their ligands PD-L1 and PD-L2, for specific tumor treatment." (PMID 36765560, 2023). "Synergy was observed with the addition of anti-PD-1 and anti-CTLA-4 treatments relative to monotherapy, with further reductions in tumor growth and a reduction of the suppressive character of myeloid cells in the TME." (PMID 37795437, 2023). "The expression of CTLA-4 seems to be higher than that of PD-L1 and is associated with a low CD4+/CD8+ ratio and high tumor grade in EC." (PMID 37368179, 2023). "We further determined that classical Ly6C+ monocytes in anti-PD-1/CTLA-4 resistant tumors are trafficked into the tumor via IFN-γ and the CCL2-CCR2 axis." (PMID 37449205, 2023). "At present, blocking B7 ligand inhibitory interactions to improve T-cell infiltration is routinely used as a strategy to guide tumor immunotherapy, especially PD-1 and CTLA-4 blocking antibodies in renal cancer and melanoma." (PMID 36717836, 2023). "One study investigated the impact of drug administration sequence and found that CTX given one day before anti-CTLA-4 therapy resulted in immune-mediated anti-tumor responses." (PMID 37920463, 2023). "Our results indicate that when PD-1/PD-L1 and CTLA-4 were inhibited, the immunogenicity in tumor tissue was higher." (PMID 37006240, 2023). "Anti-CTLA4 treated mice had a trend towards increase in tumor infiltrating CD8 + T cells compared to control mice, and the combination of propranolol and anti-CTLA4 led to a further increase in the number of tumor infiltrating CD8 + T cells." (PMID 35017664, 2022).
tumor (continued). "Given the complexity of the GBM immune microenvironment, disrupting CTLA-4/CD80 complex formation in the tumor was found to contribute to the improved survival of GBM-bearing mice." (PMID 36466873, 2022). "A tumor can utilize immune checkpoints to evade immune responses, including PD-1, PD-L1, and CTLA-4." (PMID 36105075, 2022). "Our study expands previous evidence on the immunoregulatory and anti-tumor activity of demethylating agents, including guadecitabine, when used either alone or in combination with anti-CTLA-4 in pre-clinical immunocompetent mouse models." (PMID 36397155, 2022). "Tumor cells can evade immunodetection by up-regulating immune checkpoint expression of these negative regulators PD-1 and CTLA-4 and in effect desensitize and exhaust T-cells from recognizing the tumor." (PMID 35480100, 2022). "Most commonly, these treatments were checkpoint-inhibiting antibodies such as PD-L1 or CTLA-4 inhibitors repressing the tumor ́s immune escape mechanisms." (PMID 36291947, 2022). "TGF-β and IL-10 promote the differentiation of iTregs by up-regulating the expression of Foxp3 and CTLA-4, leading to the proliferation and migration of tumor cells, resulting in poor prognosis of patients." (PMID 35541908, 2022). "In the TME of HCC, immune checkpoint molecules (PD-1, PD-L1, CTLA4, TIM3, LAG3) are associated with immunosuppressive cells to promote tumor growth and immune escape." (PMID 35757756, 2022). "In conclusion, the safety profiles and the preliminary efficacy of durvalumab in combination with tremelimumab revealed through this study support further clinical development of anti‐PD‐1/PD‐L1 and anti‐CTLA‐4 combinations in additional tumor types." (PMID 35611499, 2022). "A preclinical evaluation evidenced the high expression of OX40 and CTLA-4 in tumor infiltrating T cells, driving to the rationale of targeting it to provide an effective immune response against the tumor progression." (PMID 35785199, 2022). "For CTLA4, we found a significant variation among the high and low expression thresholds in tumor-adjacent stroma compared to those of tumor tissue." (PMID 36230846, 2022). "In another study, it showed that RFA induced anti-tumor immune response which was strongly enhanced by CTLA4 blockade, contributing to long-lasting tumor protection." (PMID 36505437, 2022). "Further experiments demonstrated that blockade of CTLA-4 stimulates the CD8+ T cell cytotoxic response against tumor cells." (PMID 35164813, 2022). "Previous studies have demonstrated vital functions of CTLA4 and PD-L1 in tumorigenesis, tumor immunity, and prognosis." (PMID 35663389, 2022). "Consistent with Luchtel’s group, they reported significantly increased Tc infiltration in the tumor microenvironment and reduced tumor growth when combining ascorbate with anti-PD-1 and anti-CTLA-4 and." (PMID 36072595, 2022). "Nevertheless, both anti-CTLA-4 and -PD-1 promoted cytotoxic T cells which seem to be involved in the reduction of tumor progression in this CT-26 model (even if only significant with anti-CTLA-4)." (PMID 35339889, 2022). "These HCCs are therefore good candidates for treatment with checkpoint inhibitors (PD-1/PD-L1 and CTLA-4 inhibitors), whose main role, which is now well known, is to allow a lifting of the inhibition of the lymphocyte immune response to the tumor cell." (PMID 36139683, 2022). "PD1/PD-L1 and CTLA-4 are important immune checkpoints for tumor immune escape, playing significant roles in tumor immunotherapy." (PMID 35754804, 2022). "To address this possibility, we measured a panel of relevant inflammatory cytokines that can be produced by anti-CTLA-4 and anti-PD-1 treatment and by adoptive transfer therapy of tumor-reactive lymphocytes." (PMID 36443756, 2022). "Pulsed radiation in combination with anti-CTLA-4 delayed primary tumor growth to a greater extent than one cycle of XRT + anti-CTLA-4 for both parental and resistant cell lines (Parental: p < 0.0001, Resistant: p < 0.0001)." (PMID 36275767, 2022).
tumor (continued). "The expression of PRF1 has been used to assess tumor-infiltrating lymphocytes in the tumor microenvironment and was related to the response of patients treated with anti-CTLA-4 therapy and anti-PD-1/PD-L1 therapy." (PMID 36097539, 2022). "ICIs act by blocking the inhibitory receptors of the immune system on T cells (PD-1 and CTLA4) and thereby activate tumor-specific T cells to destroy tumor cells." (PMID 36466840, 2022). "The thorough analysis of >4582 tumors from 90 different tumor types demonstrated in this study, that the cross-reactivities detected for our two CTLA-4 antibodies hindered the quantitation of CTLA-4+ lymphocytes in only few tumor entities." (PMID 35091676, 2022). "In order to further understand the relationship of PD-1/PD-L1/CTLA-4, it is necessary to know the interaction of their co-expression in the tumor microenvironment." (PMID 36147250, 2022). "CTLA-4 is an essential stimulatory receptor that regulates T-cell activation, which can reduce or eliminate immune cell function and encourage tumor cells to escape immune surveillance." (PMID 36171887, 2022). "Protein kinase AMPK agonists or ketogenic diets promote PD-L1 phosphorylation and disrupt its interaction with CMTM4, which contributed to inducing PD-L1 degradation and enhancing anti-CTLA4 immunotherapy in mouse tumor models." (PMID 35907881, 2022). "Immune checkpoint, especially the overexpression of PD-1/L1 and CTLA4 can generate inhibitory signals of T-cell function, thus suppressing anti-tumor immune process." (PMID 35568842, 2022). "Combination with IL‐6 blockade is not effective for sensitizing such tumor to ICI (anti‐PD‐1/anti‐CTLA‐4), but neutralization of IL‐6 along with stimulation of CD40 can cause tumor sensitization to ICI." (PMID 35301813, 2022). "Accordingly, ICIs such as anti-CTLA-4, anti-PD-1, and anti-PD-L1 can attach to these co-inhibitory receptors, thereby reactivating the immune response against tumor cells." (PMID 36612235, 2022). "We discover that anti‐PD1 mAbs and the combination with anti‐CTLA‐4/PD‐1 mAbs significantly enhance γδ T cell functions, decrease size of spheroids and increase tumour apoptosis." (PMID 35731974, 2022). "Concurrent ICOS pathway engagement further suppressed tumor growth, established a more robust memory response than anti-CTLA-4 alone, and increased survival in those models." (PMID 35326731, 2022). "To further explore the role of G6PD in the tumour immune microenvironment, we also analysed the association between G6PD and immune checkpoint molecules (PDCD1, CD274 and CTLA4)." (PMID 35712981, 2022). "Tumor cells can evade the immune response by losing the expression of tumor antigens and/or actively inhibiting the responses of effector cells via inhibitory ligands, such as CTLA-4 and PD-L1." (PMID 36939758, 2022). "A higher ImmuneScore and increased PD-L1 and CTLA-4 expression levels were identified in Cluster 1, suggesting a more immunosuppressive tumor ecosystem." (PMID 35990696, 2022). "In contrast, blockade of CTLA-4 and PD-1 improves the capacity of immune cells to clear tumor cells." (PMID 35634346, 2022). "Strikingly, the authors observed that CTLA4-TβRII trap alone inhibits the growth of the TNBC tumor model better than a combination treatment using anti-CTLA-4 plus anti-PD1." (PMID 35577211, 2022). "Blockade of CTLA-4 has been shown to augment T-cell activation and proliferation, which promotes anti-tumor immune response." (PMID 36079112, 2022). "After binding PD1, PD-L1, or CTLA4, ICIs remove the block for the immune system, reversing neoplastic immune evasion and promoting anti-tumor response in many solid tumors." (PMID 35328239, 2022). "Inosine activation of the A2AR on T cells is itself complex: inosine either prevented Th1 differentiation and blunted anti-tumor immunity in anti-CTLA4-treated mice or, conversely, enhanced both, when co-supplied with IFNγ in vitro and a TLR9 agonist in vivo." (PMID 34986329, 2022).